INS (insulin)
Diseases named in the same sentence as INS in open-access papers (continued):
Sharing a sentence is not in itself a finding about the gene and the disease.
Hypoglycemia (continued). "The two-fold introduction of SZC alongside changes in patient care after the administration of insulin/dextrose resulted in more appropriate use of insulin/dextrose, as well as a significant (73%) reduction in the iatrogenic burden of hypoglycaemia (P = 0.04)." (PMID 38871123, 2024). "The assumption is that SB boosts the prandial insulin to avoid glycemic spikes whilst removing the basal insulin to prevent postprandial hypoglycemia." (PMID 38257156, 2024). "Patients with IGF-2-mediated hypoglycemia present with fasting hypoglycemia characterised by suppressed endogenous insulin, ketones, growth hormone, and IGF-1." (PMID 38432069, 2024). "Considering the contributing severe and prolonged hypoglycemia, both an insulinoma and external abuse of insulin were discussed; however, they were excluded due to the abdominal sonography and by measuring C-peptide concentrations." (PMID 41542255, 2024). "TH mRNA levels were found to increase within the adrenal gland of non-diabetic rats subjected to seven episodes of both repeated insulin-induced hypoglycaemia and 2DG-induced glucoprivation." (PMID 38392992, 2024). "Transitional neonatal hypoglycemia and perinatal stress-induced hyperinsulinism likely share a common mechanism, leading to elevated insulin concentrations, albeit transiently in transitional neonatal hypoglycemia." (PMID 38792494, 2024). "Dapagliflozin does not impair normal endogenous glucose production in response to hypoglycemia and acts independently of insulin secretion and insulin action." (PMID 39000033, 2024). "The program’s 12-session curriculum emphasized intensive insulin therapy and self-management, including blood glucose monitoring, diet, and hypoglycemia prevention." (PMID 39765957, 2024). "There are very few studies investigating the effects of insulin-induced hypoglycaemia on the gene expression or the protein expression of the peptides in the adrenal gland." (PMID 38392992, 2024). "In contrast, recipients with hypoglycemia and persistent bioluminescence signals showed a significant presence of insulin-positive cells in their grafts." (PMID 38920672, 2024). "Increased tissue sensitivity to insulin, mediated by factors like insulin-like growth factor-1, can also promote the development of hypoglycemia." (PMID 39555226, 2024). "Recurrent hypoglycemia in the setting of suppressed insulin, C-peptide, growth hormone, and beta-hydroxybutyrate levels is suggestive of NICTH." (PMID 39372824, 2024). "Hypoglycaemia was observed as quadra-peaked in insulin users and double-peaked in oral hypoglycaemic agent users." (PMID 38975379, 2024). "We evaluated the effects of switching from Deg to Gla-300 on the day-to-day GV and the frequency of hypoglycemia in patients with insulin-dependent type 1 diabetes treated with Deg-containing basal-bolus insulin therapy (BBT)." (PMID 38541176, 2024). "Our data, as the others studies with Gla-300, in relation to reduce the hypoglycemia prevalence was similar a recent study with another long action basal insulin (Degludec) in T1D." (PMID 38982528, 2024). "Approaches to preventing hypoglycemia include glucose monitoring, patient education, meal planning, insulin therapy adjustment, glucose sensors, and AHCL pumps." (PMID 38894740, 2024). "Self-reported hypoglycemia was more frequent in the insulin group and correlated with lower treatment satisfaction." (PMID 39765957, 2024). "Sulfonylureas stimulate insulin release from pancreatic cells and have an extrapancreatic hypoglycemic effect, making them more likely to induce hypoglycemia." (PMID 38918852, 2024). "Nevertheless, hypoglycemia was confirmed in all 145 cases and either serum insulin or C-peptide levels were suppressed." (PMID 39689018, 2024). "It enhances the tumor cell killing effect through insulin‐induced hypoglycemia in combination with chemotherapy." (PMID 39629677, 2024).
Hypoglycemia (continued). "Insulin therapy adherence can be influenced by socioeconomic factors, treatment complexity, and fear of hypoglycemia." (PMID 39062173, 2024). "Later, in the so-called spent-out phase, a decrease in insulin secretion and hypoglycemia of the insulin-dependent phagocytes will impair the microglial scavenge of Aβ, which precipitously increases the intracellular burden by aggregates." (PMID 39684795, 2024). "Excessive correction frequently leads to postprandial hypoglycemia due to the “stacking insulin effect”." (PMID 39062173, 2024). "Insulin therapy in T1D is based on long- and short-acting insulins aiming good glycemic control and avoiding hypoglycemia and weight gain." (PMID 38982528, 2024). "Loureirin B, a dihydrochalcone analog, extracted from Sanguis Draconis, which promotes insulin secretion and hypoglycemia." (PMID 38799166, 2024). "Other side effects reported in the saxagliptin group included an increase in hypoglycemia, particularly among patients who were also receiving insulin or sulfonylureas." (PMID 39768866, 2024). "Studies in patients with NDM due to activating mutations in KCNJ11 found that these patients were able to effectively switch from insulin to high-dose SU, with resulting tight glycemic control while avoiding hypoglycemia." (PMID 38267622, 2024). "Machine learning research for managing T1D focuses on the safety of AID systems, improving the insulin dosing decision algorithms, improving blood glucose prediction, predicting hypoglycemia, and predicting insulin sets and blood glucose sensor failures." (PMID 39654139, 2024). "Several patient-related factors contribute to this issue, including inadequate insulin dosing, inappropriate carbohydrate counting, fear of hypoglycemia, and use of an unstructured SMBG." (PMID 37996773, 2024). "This highlights the necessity for more research on insulin types, doses, and target glucose levels tailored to individual characteristics, with a crucial emphasis on preventing hypoglycemia." (PMID 38330019, 2024). "Another promising alternative to insulin are Sodium Glucose Transporter-2 (SGLT-2) inhibitors, as they have a low risk for hypoglycemia." (PMID 38281042, 2024). "Localizing studies should only be performed once endogenous insulin-mediated hypoglycemia has been demonstrated." (PMID 39125476, 2024). "This approach is in contrast to the traditional rigid recommendation of dividing the daily caloric intake into 2 meals that must be fed (and then consumed in full and digested) at the times of insulin injections in order to avoid hypoglycemia." (PMID 38831362, 2024). "Some reviews and meta-analyses report similar risks of hypoglycemia and adverse effects as for regular insulin, while others highlight the superiority of RAIAs." (PMID 39457586, 2024). "Through the modulation of insulin secretion, this medication lowers tumor growth and alleviates hypoglycemia by targeting somatostatin receptors on tumor cells." (PMID 39723310, 2024). "Level 2 hypoglycemia within 12 h of IV insulin discontinuation was also lower in the Early group (4% vs. 12%; p = 0.003)." (PMID 39136541, 2024). "In T1DM patients, metformin is usually combined with insulin as it has been demonstrated to better control blood glucose levels, reducing the risks of hypoglycemia, and decreasing the total dose of insulin needed." (PMID 39451273, 2024). "The present study delves into alterations in antioxidants and histopathological changes in the brain subsequent to high doses of insulin administration and severe hypoglycemia." (PMID 39004753, 2024). "Based on the pharmacokinetic and pharmacodynamic profiles of the RAIAs, hypoglycemia is the most common and significant short-term ADR and is most likely directly caused by insulin." (PMID 39457586, 2024). "For instance, inaccuracies in CGM data during surgery can lead to inappropriate insulin dosing, resulting in iatrogenic hypoglycemia." (PMID 39458119, 2024).
Hypoglycemia (continued). "Acute insulin administration produced a similar profile and degree of hypoglycaemia in the two groups." (PMID 38109257, 2024). "In the per-protocol analysis, early basal insulin therapy resulted in significantly higher hypoglycemia rates but reduced odds for overt PTDM." (PMID 38337487, 2024). "Literature reported that patients on insulin are more likely to suffer from severe hypoglycemia, most probably due to insulin dose miscalculation." (PMID 39583394, 2024). "ZT-01 treatment prevented hypoglycemia in 37% of rats who were administered bolus insulin to induce mild-to-moderate hypoglycemia." (PMID 38510652, 2024). "In RCTs comparing GLP-1RA and placebo, insulin doses were reduced before GLP-1RA initiation to avoid hypoglycemia, and close monitoring and insulin adjustments were done periodically." (PMID 39906033, 2024). "Continuing Otto Warburg's work on limiting glucose to starve cancer, we employ the use of insulin to induce short term hypoglycemia in the Warburg therapy protocol." (PMID 39629677, 2024). "In one trial conducted on a small number of people with symptomatic PBH, empagliflozin (a selective SGLT-2 inhibitor) reduced peak postprandial glucose, reduced insulin levels and reduced episodes of hypoglycaemia during an MMT." (PMID 38451861, 2024). "While Ghr-KO mice can be considered glucose intolerant, they nevertheless showed fasting hypoglycemia, suggesting insulin hypersensitivity as in human LS patients." (PMID 38960990, 2024). "Neonatal transient hyperinsulinism manifested on the 18th day, characterized by a biochemical finding of insulin at 10 mU/L accompanied by hypoglycemia necessitating treatment with diazoxide and chlorothiazide." (PMID 39466809, 2024). "While infusing excessive amount of exogenous insulin leads to a situation called hypoglycemia in which BGL reaches less than 50 mg/dl, this in turn leads to instant coma and death." (PMID 38186949, 2024). "Following single-donor, marginal-dose IT, this established transplant strategy effectively prevented hypoglycemia and restored insulin independence in all 8 recipients." (PMID 38669398, 2024). "Among the patients in our study, 55% of patients had agents that can induce hypoglycemia, such as insulin, sulfonylureas, and glinide." (PMID 39610482, 2024). "It is characterized by a combination of compromised physiological defenses against hypoglycemia, i.e., a decrease in glucose lowering insulin, and an increase in the glucose raising hormones glucagon and adrenaline." (PMID 39375537, 2024). "Overall, KO males were more affected than their female counterparts as they displayed pronounced fasting hypoglycemia and increased and persistent insulin sensitivity over a 14-week follow-up." (PMID 38519536, 2024). "At the very least, it is difficult to link the insulin and phentolamine mesylate administered during the surgery to the persistence of hypoglycemia." (PMID 39498182, 2024). "While glucagon’s release is stimulated by hypoglycemia, starvation, exercise, and protein-rich meals, insulin release is stimulated by a hyperglycemic condition." (PMID 38921471, 2024). "Glucagon-loaded micelles injected into mice preventedor reversed deep hypoglycemia when administered prior to or duringan insulin challenge." (PMID 39634211, 2024). "In diabetic rats not treated with insulin, the plasma adrenaline response to a single episode of insulin-induced hypoglycaemia was already significantly reduced compared to normal rats." (PMID 38392992, 2024). "The release of systemic adrenaline in response to insulin-induced hypoglycemia is dependent upon TRPC5 channel activation in adrenal cells." (PMID 39375537, 2024). "In summary, we show here that an SSTR2 antagonist can improve the glucagon counterregulatory response to insulin-induced hypoglycemia and prevent, or at least delay, the onset of hypoglycemia by up to −40 min in a rat model of T2D." (PMID 38510652, 2024).
Hypoglycemia (continued). "Hypoglycemia is a common complication after the administration of insulin, which is a concern in patients with reduced kidney function." (PMID 39274318, 2024). "The most common adverse effects of iSGLT2 include genital mycotic infections,hypoglycemia (especially with concomitant use of insulin or insulin secretagogues intype 1 diabetics) and extracellular volume depletion." (PMID 38498673, 2024). "Insulin pumps can help patients with a history of hypoglycemia by reducing the frequency of episodes and raising HbA1c levels, which is helpful." (PMID 39065641, 2024). "On induced hypoglycaemia, the grafts efficiently shut down insulin secretion by 90% from fasted levels, indicating effective glucose sensing." (PMID 38871836, 2024). "One of the most common aetiologies of recurrent hypoglycemia and glycemic variability is lipodystrophy, which occurs due to improper insulin injection techniques practices, leading to severe complications." (PMID 38304656, 2024). "Hypoglycaemia is the most common complication of insulin treatment, reportedly affecting people with type 1 diabetes on a twice weekly basis." (PMID 38331900, 2024). "Even so, we hold that focus should turn to the potential of enhancing the absorption of insulin from the SC tissue by utilizing the vasodilative properties of glucagon and, concomitantly, using glucagon to treat and prevent hypoglycemia." (PMID 37715091, 2024). "The 72-hour fasting test ended prematurely because of hypoglycemia, and the plasma insulin levels simultaneously increased slightly from 6.2 mIU/L (43 pmol/L) to 9.2 mIU/L (64 pmol/L), proposing a possible insulinoma." (PMID 39659391, 2024). "Insulin dosing strategies to prevent hypoglycemia were the focus of previous studies in which reduced doses resulted in fewer hypoglycemic episodes without significantly reducing treatment efficacy, even in patients with reduced kidney function." (PMID 39274318, 2024). "Insulin autoimmune syndrome (IAS), or Hirata’s disease, is a rare disease characterized by episodes of hypoglycemia with elevated levels of insulin secondary to high concentrations of insulin autoantibodies." (PMID 39347250, 2024). "Consistent hypoglycemia, suppressed blood insulin level, C-peptide, and low serum insulin-like growth factor-II (IGF-II) levels, in contrary to normal or high levels of IGF-II, are the hallmarks of the DPS." (PMID 39435031, 2024). "This is relevant since it has been observed that insulin-treated females, in particular, were more likely to experience hypoglycaemia." (PMID 39407915, 2024). "Hypoglycemia has always been considered a dangerous side effect of the treatment of DM with insulin or insulin secretagogues." (PMID 38529396, 2024). "Insulinomas are the most common neoplasms of the endocrine pancreas in dogs, leading to persistent hypoglycemia due to inappropriate insulin secretion." (PMID 39595353, 2024). "The biochemical diagnosis of insulinoma is typically established through the demonstration of hypoglycemia resulting from excessive endogenous insulin production." (PMID 39100462, 2024). "Although the mainstay treatment of exogenous insulin injections can help T1DM patients achieve normoglycemia, the daunting risk of life-threatening hypoglycemia unawareness remains interconnected." (PMID 39553396, 2024). "During hospitalization at the Department of Nuclear Medicine and Endocrine Oncology, the pathognomonic for the diagnosis of insulinoma, hypoglycemia (1.97 mmol/L) with inadequately high levels of insulin (24 uIU/mL) and peptide (3.14 ng/mL), was found." (PMID 39057179, 2024). "Physical activity level, BMI, weight, insulin delivery method, blood glucose monitoring method, HbA1c, severe hypoglycemia, and hospital admissions with DKA." (PMID 39867016, 2024).
Hypoglycemia (continued). "Somatostatin infusion was shown to decrease AVP secretion during ITT despite similar glucose nadir, while AVP and oxytocin responses during ITT were completely abolished when the concomitant infusion of glucose prevented insulin-induced hypoglycemia." (PMID 39262672, 2024). "Typically, when the plasma glucose concentration decreases, first, pancreatic beta cells stop insulin, followed by increased secretion of glucagon and adrenaline to prevent hypoglycemia." (PMID 38334891, 2024). "Given that hypoglycaemia occurred at a delayed time point, capillary blood glucose should be monitored hourly for a minimum of 6 h after insulin/dextrose administration." (PMID 38871123, 2024). "The authors had achieved insulin-induced moderate hypoglycemia by a bolus injection of 1–2 μg/kg of regular insulin followed by a continuous infusion of insulin in 0.9% normal saline." (PMID 38235171, 2024). "The newer technology, “automated insulin delivery” (AID) or “hybrid closed-loop system” (HCL), is equipped with control algorithms that can automatically suspend insulin infusion to prevent hypoglycemia." (PMID 38397994, 2024). "The yearly NBI of IGlar adoption in the treatment of patients with T2D and severe hypoglycemia from NPH insulin was 174.9 million THB (5.1 million USD)." (PMID 39877917, 2024). "Factors that contribute to hypoglycemia in T1D include excess insulin, decreased food consumption, exercise, sleep and alcohol ingestion." (PMID 39944479, 2024). "Hypoglycemia was reported for all sulfonylurea and insulin-related fatalities, and for two (20%) of the metformin-related deaths." (PMID 39300573, 2024). "Unlike dextrose infusions, octreotide, like somatostatin, directly suppresses the pancreatic production of insulin, preventing rebound hypoglycemia." (PMID 39347364, 2024). "In a second phase, the dissociation of insulin from immune complexes with autoantibodies creates a relative excess of insulin, resulting in the lowering of the glycemia under the threshold of hypoglycemia." (PMID 38952701, 2024). "The likelihood of developing hypoglycaemia, in those treated for acute hyperkalaemia, was significantly greater in patients treated with insulin/dextrose and those treated in the initial observation period 2019." (PMID 38871123, 2024). "Acarbose can be used when dietary modifications fail to prevent post-prandial hypoglycaemia, by slowing glucose absorption to decrease the glycaemic peak followed by insulin release." (PMID 39153498, 2024). "The total budget included either the cost of insulin or a combination of the costs of insulin and the expense related to severe hypoglycemia." (PMID 39877917, 2024). "Subsequently, SAPs were developed with the Low Glucose Suspend (LGS) and Predictive Low Glucose Suspend (PLGS) function, automatically interrupting the basal insulin infusion in case of hypoglycemia or predicted hypoglycemia." (PMID 38966218, 2024). "This study further reported the possibility of hypoglycemia due to increased insulin, by the stimulation of pancreatic secretion or by activation of the inactive form." (PMID 38926797, 2024). "Hypoglycemia to PG 51 mg/dL (2.8 mmol/L) occurred at +150 min into the OGTT with plasma insulin of 6.68 uIU/mL (46.4 pmol/L) and peak insulin level of 84.01 uIU/mL (583.4 pmol/L) noted at +30 min." (PMID 39483531, 2024). "Odds ratios with 95% CI are presented for comparisons of glyburide vs insulin, metformin vs insulin, and metformin vs glyburide for neonatal consequences such as macrosomia, higher gestational age, infant hypoglycemia, and birth weight." (PMID 39479091, 2024). "The Warburg therapy's use of insulin pharmacologically induces hypoglycemia overcoming dietary compliance issues while creating a period where cancerous tumors are deprived of much of their needed glycose so they can be treated with chemotherapy." (PMID 39629677, 2024).